ENSG00000257563 (microRNA 3180-3)
Gene: Long non-coding RNA gene on chromosome 16 (18,402,146 to 18,403,604, forward strand). Ensembl gene ENSG00000257563.
Gene Ontology:
Biological process: miRNA-mediated post-transcriptional gene silencing